MIR509-1 (microRNA 509-1)
Synonyms: hsa-mir-509; hsa-mir-509-1; MIRN509; MIRN509-1; mir-509-1
Gene: MicroRNA gene on chromosome X (147,260,532 to 147,260,625, reverse strand). Ensembl gene ENSG00000208000.
Homologues: Orthologues: chimpanzee ptr-mir-509a-1 (99% identical), macaque mml-mir-509-2 (95% identical), macaque mml-mir-509-1 (94% identical), mouse Mir509 (60% identical), rabbit ocu-mir-506 (37% identical). Paralogues in human: MIR514A1 (81% identical), MIR509-3 (79% identical), MIR514A2 (77% identical), MIR514A3 (77% identical), MIR514B (64% identical), MIR507 (62% identical), MIR506 (54% identical), MIR513A2 (52% identical), MIR513B (52% identical).